GJA1 (gap junction protein alpha 1)
Diseases named in the same sentence as GJA1 in open-access papers (continued):
Sharing a sentence is not in itself a finding about the gene and the disease.
melanoma (87 papers, 2005 to 2026). A malignant, usually aggressive tumor composed of atypical, neoplastic melanocytes. "In three melanoma cell lines, we also showed the loss of GJA1/Cx43 and the differential expression of GJB1/Cx32, GJB2/Cx26, GJA3/Cx46 and GJC3/Cx30.2." (PMID 30717194, 2019). "Metastatic melanomas showed the loss of GJA1 (Cx43) protein, the increase in cytoplasmic GJB2 (Cx26), and the upregulation of both GJC3 (Cx30.2) and GJB1 (Cx32) through melanoma progression, compared to melanocytes." (PMID 40227837, 2025). "The up-regulation of GJA1 expression implicates a crucial link between melanoma cells and endothelial cells, thus enhancing tumor metastasis in melanoma." (PMID 35479936, 2022). "This HIF-1α-dependent Cx43 expression in cardiac cells supports our previous evidence showing that HIF-1α binds GJA1 promoter, inducing Cx43 expression in hypoxic melanoma cells." (PMID 33066331, 2020). "In GSE8401 arrays, metastatic melanomas from xenograft models showed downregulated GJA1 (Cx43; LogFC = −2.8; p < 0.001), GJB3 (Cx31; LogFC = −1.8; p < 0.001) and GJB5 (Cx31.1; LogFC = −1.1; p < 0.001) gene expression compared to primary melanomas." (PMID 30717194, 2019). "The qRT-PCR results showed that the expression levels of four genes, FCGR2, GBP4, SLC5A3 and GJA1, in melanoma cells were different from that in normal melanocyte, which was consistent with the statistical results of the samples we obtained in the public database." (PMID 40652057, 2025). "GJA1 was considered to potentially play a significant role in melanoma and could predict patients’ response to PD-1 immunotherapy." (PMID 38287304, 2024). "In datasets using GSE3189 arrays, melanomas showed downregulated GJA1 (Cx43; LogFC = −4.1; p < 0.001), GJB3 (Cx31; LogFC = −3.4; p < 0.001), GJB5 (Cx31.1; LogFC = −3.3; p < 0.001) and upregulated GJB1 (Cx32; LogFC = +1.5; p < 0.001) gene expression compared to nevi." (PMID 30717194, 2019). "Gap junction protein alpha 1 gene (GJA1), also called connexin 43 (Cx43), has a tumor suppressor function and can inhibit the progression of melanoma." (PMID 40652057, 2025). "Using WGCNA combined with supervised machine learning algorithms, we identified a novel CAFs-related panel, including six genes (CDK14, SYNPO2, TCF4, GJA1, CPXM1, TFPI), which can distinguish the response of melanoma patients under anti-PD-1 immunotherapy." (PMID 35479936, 2022). "In silico data revealed downregulation of GJA1/Cx43 and GJB2/Cx26 mRNA, in addition to upregulated GJB1/Cx32, during melanoma progression." (PMID 30717194, 2019). "Genes such as KRT14, GJA1, S100A7, S100A9, and EHF were higher in most melanomas while genes such as CITED-1, GDF15, QPRT, OCA2, c-MET and MME were more highly expressed in NHEM." (PMID 18442402, 2008). "Similarly, impairment of NK tumor cytotoxicity is demonstrated in melanoma through the hypoxia-induced autophagy mechanism, which mediates degradation of wild-type Gap junction α-1 protein (GJA1)(connexin 43 (CX43)), a key substance of intercellular gap junctions." (PMID 36833401, 2023). "Cx43 (GJA1) immunostaining showed punctuate cytoplasmic and focal membranous pattern in primary melanocyte culture (MC), but no reaction in melanoma lines A2058, HT199 or WM983/A." (PMID 30717194, 2019).
Ventricular arrhythmia (78 papers, 2007 to 2026). "In both patients and a mouse model with arrhythmogenic cardiomyopathy, levels of GJA1-20k are reduced in the heart, leading to a decrease in Cx43 expression at the ICDs and contributing to ventricular arrhythmias." (PMID 39936974, 2025). "For instance, a low-dose introduction of GJA1-20k can reduce ventricular arrhythmia in mouse models of arrhythmogenic cardiomyopathy." (PMID 37639557, 2023). "Provided that detected lateral Cx43 (GJA1) forms functional channels, this may explain why infant and children’s hearts rarely show ventricular arrhythmias." (PMID 24751918, 2014).
myocardial infarction (74 papers, 2008 to 2025). Gross necrosis of the myocardium, as a result of interruption of the blood supply to the area, as in coronary thrombosis. "Cluster two also included the SOD1 gene but it also included other genes with high DPI such as GJA1, associated with cancer, hypertensive disease, heart anomalies and S100B, associated with schizophrenia, myocardial infarction, mental depression and bipolar disorders." (PMID 34570756, 2021). "In vivo assays using a mouse model of ischemia/reperfusion (I/R) injury with GJA1-20k overexpression showed a significant reduction in cardiac damage and myocardial infarct size compared to controls." (PMID 39765713, 2024). "Gja1-20k is cardioprotective in the context of IR injury as the overexpression of alternatively transcribed Cx43 reduces myocardial infarction both in vitro and in vivo." (PMID 35860665, 2022). "The results indicate that stress responsive internally translated GJA1-20k stabilizes polymerized actin filaments to stimulate non-canonical mitochondrial fission which limits ischemic-reperfusion induced myocardial infarction." (PMID 34608863, 2021). "Researchers have shown that the injection of miR-1 into the ischemic myocardium of rats with myocardial infarction (MI) led to decreases in GJA1 and KCNJ2, which are the target genes of miR-1." (PMID 34646152, 2021). "Adult mice heterozygous for the internal GJA1-20k start have normal baseline cardiac phenotypes, yet suffer almost complete myocardial infarctions once subjected to I/R injury." (PMID 34608863, 2021). "It has been found that AAV9-mediated GJA1-20k overexpression in mouse heart depresses mitochondrial respiration, which has the beneficial effect of limiting myocardial infarction after ischemic-reperfusion (I/R) injury." (PMID 34608863, 2021). "Therefore, GJA1-20k induced decreases in ROS production could limit the amount of I/R injury induced by myocardial infarction." (PMID 34608863, 2021).
heart failure (73 papers, 2011 to 2025). Inability of the heart to pump blood at an adequate rate to meet tissue metabolic requirements. "As a pertinent issue, the GJA1 SNPs including rs1015451 have recently been reported to be associated with heart failure and a reduced ejection fraction." (PMID 33510344, 2021). "Mislocalization or dysfunction of Gja1 because of hypertension-induced myocardial remodeling might cause lethal arrhythmias and heart failure." (PMID 33083107, 2020). "Additionally, the role of GJA1-20k in maintaining mitochondrial homeostasis is particularly relevant in the heart, where mitochondrial dysfunction is a key factor in the pathogenesis of ischemic heart disease and heart failure." (PMID 39765713, 2024). "Recently, several lines of evidence have shown that alterations in GJA1 expression and distribution occur in hearts from patients with HCM, dilated cardiomyopathy (DCM), MI, and heart failure." (PMID 33048975, 2020).
lung carcinoma (61 papers, 2006 to 2025). "The silencing of GJA1 gene may cause a reduction of paclitaxel efficiency in gastric cancer, and cisplatin-resistance in lung cancer." (PMID 35664298, 2022). "The role of GJA1 encoding Cx43 is controversial in lung cancer and, although this gene is highly expressed, there are only modest changes to its gene expression in the tumours, with a slight downregulation in LUAD (0.31-fold) and slight upregulation in LUSC (1.33-fold)." (PMID 30845770, 2019). "Additionally, GJA1 mutations are frequent in some hypermutated lung cancers." (PMID 30717421, 2019). "Thus, this marker in our model is critical for early-stage lung cancer, and additional studies are needed to investigate potential targets to reverse the inhibition of GJA1 function observed in response to the MCA/LMW PAH mixture/B[a]P treatment." (PMID 39771097, 2024). "The decreased expression of Cx43 in lung cancer has been attributed to epigenetic silencing of GJA1, but whether this is true in lung CSCs is not known." (PMID 30717421, 2019). "Other genes inhibited by EGFR signaling, such as gap junction protein alpha 1 (Gja1), a mediator for cell-cell communication in lung epithelial cells that is down-regulated in human and mouse lung cancer, were elevated in the BALB mice (Gja1, confirmed by PCR, data not shown)." (PMID 19925653, 2009). "Similarly, overexpression of GJA1 was also found to inhibit the growth of lung cancer cells (LH7)." (PMID 33299882, 2020). "While many studies have explored the role of GJA1 (connexin 43) in NSCLC, the role of GJBs in lung cancer remains poorly understood." (PMID 38562019, 2024). "The TIMER2.0 analysis demonstrated a significant positive correlation between GJA1 expression and infiltration level of total macrophages, as well as M1 macrophages, suggesting that GJA1 may be involved in macrophage‐mediated immune responses in lung carcinoma." (PMID 39592436, 2024). "A network of interactions between proteins TUBB2B, MAPK7, TUBAL3, MAP2K5, and GJA1 (Cx43) suggests that reduced expression of MAPK and tubulin genes could be responsible for the attenuation of the gap junction pathway and insensitivity of lung cancer cells to cisplatin." (PMID 38351531, 2024).
atrial fibrillation (50 papers, 2013 to 2025). A disorder characterized by an electrocardiographic finding of a supraventricular arrhythmia characterized by the replacement of consistent P waves by rapid oscillations or fibrillatory waves that vary in size, shape and timing and are accompanied by an irregular ventricular response. "Removal of mouse homologues of atrial fibrillation-associated regions in vivo uncovers a distal regulatory region involved in Gja1 (Cx43) expression." (PMID 31628324, 2019). "Transcripts of additional atrial fibrillation associated genes, such as those encoding the gap junction proteins GJA1 and GJA5, and the transcription factor, GATA541, and signaling pathways were also differentially expressed in the LA and RA." (PMID 30224797, 2018). "A previous investigation demonstrated that GJA1 was associated with the progression of atrial fibrillation, but might be important gene signatures of T1D in patients with atrial fibrillation." (PMID 33827531, 2021). "For example, miR-328 induces atrial fibrillation by promoting atrial electrical remodeling, and miR-1 regulates cardiac arrhythmogenic potential by targeting relevant ion-channel-encoding genes KCNJ2 and gap junction protein alpha 1 (GJA1) in cardiac ischemic injuries." (PMID 30292140, 2018).
diabetes (49 papers, 2012 to 2026). "A well-known example is SOD1 related to neuroinflammation, hyperthyroidism, hypertensive disease (associated also with GJA1), diabetes mellitus (associated also with IGF2BP2) and depressive disorders (associated also with S100B)." (PMID 34570756, 2021). "Recent reports in patients with type 2 diabetes mellitus manifested the expression of tight junction markers, including GJA1, was significantly suppressed by hyper-activating Apelin (APLN) peptide and downregulated in diabetic testis." (PMID 38390397, 2023).
cardiac hypertrophy (44 papers, 2010 to 2025). "Cardiac hypertrophy is known to be regulated by micro RNAs, and the upregulation of muscle-specific miR-1 noted in hypertrophy can affect cardiac arrhythmogenicity by targeting the GJA1 gene which encodes Cx43." (PMID 36830700, 2023). "In a rat model of cardiac hypertrophy, in vitro overexpression of GJA1-20k in cardiomyocytes enhanced energy metabolism by increasing the mitochondrial membrane potential and respiration and decreasing ROS generation." (PMID 39936974, 2025). "In cardiac hypertrophy (CH), whether observed in a spontaneously hypertensive rat model or induced in vitro by angiotensin II (Ang II) on cardiomyocytes, there is a downregulation of GJA1-20k expression mediated by Jak2 signaling, associated with reduced gap junction presence at the ICDs." (PMID 39936974, 2025). "It has been reported that the lateralization of GJA1 occurs in cardiomyocytes of compensated cardiac hypertrophy in patients with aortic stenosis." (PMID 33048975, 2020). "Indeed, reductions in the expression and heterogeneous redistribution of GJA1 have been reported in decompensated human hypertrophy, arrhythmogenic cardiomyopathy, ischemic samples, and induced -pluripotent stem cell (iPS)-derived cardiomyocytes from patients with cardiomyopathy." (PMID 33048975, 2020).
prostate carcinoma (44 papers, 2010 to 2025). A carcinoma that arises from epithelial cells of the prostate gland. "Also connexin-43 (GJA1 gene), a gap junction protein, once internalized is degraded by autophagy after SQSTM1/p62 binding and delivery to autophagosome and, interestingly, connexin-43 has been observed to be downregulated in breast and prostate cancers." (PMID 34944948, 2021).
myocardial ischemia (43 papers, 2013 to 2025). A disorder of cardiac function caused by insufficient blood flow to the muscle tissue of the heart. "Taken together, internally translated peptide “GJA1-20k” is essential for full-length Cx43 protein trafficking to cell membrane and maintains gap junction stability in stress situations such as cardiac ischemia." (PMID 35399255, 2022). "Furthermore, the cardiac-specific overexpression of GJA1-20k enhances the trafficking of Cx43 to IDs, preserving GJIC during myocardial ischemia." (PMID 32842488, 2020).
cardiomyopathy (41 papers, 2008 to 2025). A disease of the heart muscle or myocardium proper. "Upregulated genes linked to cardiomyopathy included Pkp2, Dst, Dsg2 and Jup; downregulated genes included Pkp1, Dsg1a, Pkp4, Vcl, Gja1 and Ctnna1." (PMID 26935106, 2016). "These genes are described for being important for cardiac function and related cardiomyopathies directly linked to gene defects/mutations or genetic variation within these genes (DES, DSP, GJA1)." (PMID 41275133, 2025). "Genetic mutations and aberrant functions of DES, DSP, GJA1, and SMOC2 are implicated in cardiomyopathies through dysregulation of key cellular processes, including tissue remodelling, intercellular communication, and extracellular matrix regulation." (PMID 41275133, 2025). "Thus, the potential protective role of GJA1-20k in cardiomyopathy lends urgency to elucidating the cis and trans acting factors governing GJA1 translation." (PMID 32164190, 2020).
depression (37 papers, 2013 to 2026). "Multiple mRNAs regulated by chronic corticosterone exposure in this study are reported to be changed in the same direction in human depression (e.g., downregulation of Gja1, Slc1a2, and Slc1a3)." (PMID 23966905, 2013).
Cerebral ischemia (36 papers, 2010 to 2025). Restriction of arterial blood supply to the brain associated with insufficient oxygenation to support the metabolic requirements of the tissue. "Our previous transcriptomic analysis revealed the significant upregulation of TNC and GJA1 in the SVZ following transient global cerebral ischemia." (PMID 40003865, 2025). "Future research may clarify the molecular mechanisms by which cerebral ischemia regulates the expression of TNC and GJA1." (PMID 40003865, 2025).
colorectal cancer (35 papers, 2011 to 2025). A primary or metastatic malignant neoplasm that affects the colon or rectum. "In colorectal cancer, the loss of GJA1 expression is positively correlated with patient metastasis and poor prognosis." (PMID 39132501, 2024). "Overexpression of GJA1 can inhibit the progression of colorectal cancer and enhance cancer cell sensitivity to 5-fluorouracil (5-FU)." (PMID 39132501, 2024). "For example, the upregulation of GJA1, or Cx43, sensitizes colorectal cancer cells to doxorubicin, florouracil, oxaliplatin, and taxol-based treatments." (PMID 39594803, 2024). "Moreover, the high expression of GJA1 predicted a poor prognosis in colorectal cancer and was positively correlated with immune cell infiltration." (PMID 35279164, 2022). "However, down regulation of GJA1 through its promoter hyper-methylation was shown not to be true for in human colorectal cancer, and therefore silencing of the GJA1 was suggested be mediated by other mechanisms through estrogen activation." (PMID 23675859, 2013).
hepatocellular carcinoma (31 papers, 2008 to 2025). A malignant tumor that arises from hepatocytes. "Specifically, studies in hepatocellular carcinoma cells reveal that the dysregulation of GJA1 (Cx43) expression can enhance cell invasion and migration as well as disrupt normal cell mitosis." (PMID 38956497, 2024). "Moreover, GJA1 was shown to promote hepatocellular carcinoma progression via TGF-β activation and enhancement of EMT process." (PMID 35371339, 2022). "Gap junction protein, alpha 1 (GJA1), which is correlated with recurrences and unfavorable prognoses in hepatocellular carcinomas (HCCs), is one of the specific proteins expressed by activated hepatic stellate cells (HSCs)." (PMID 34693020, 2021). "Expression of GJA1 was compared between HCCs and nontumor tissues (NTs), between hepatic cirrhosis and NTs, and between primary and metastatic HCCs using transcriptomic datasets from the Gene Expression Omnibus and the Integrative Molecular Database of Hepatocellular Carcinoma." (PMID 34693020, 2021).
osteosarcoma (30 papers, 2009 to 2025). A usually aggressive malignant bone-forming mesenchymal neoplasm, predominantly affecting adolescents and young adults. "Gap junction proteins have a pivotal role in the modulation of the inflammatory response and GJA1 3′UTR was demonstrated to be a direct target of miR-23a-3p in an osteosarcoma cell model." (PMID 33519486, 2020). "MiR-23a impairs bone differentiation in osteosarcoma via down-regulation of GJA1." (PMID 27191270, 2016).
Hypertension (29 papers, 2014 to 2025). The presence of chronic increased pressure in the systemic arterial system. "High-salt intake-induced hypertension increases TRPP2 expression in VSMCs, which may in turn change Ca2+ dynamics as well as the expression of Gja1." (PMID 33083107, 2020).
atherosclerosis (28 papers, 2015 to 2025). A disease characterized by the build-up of fatty material and calcium deposition in the arterial wall resulting in partial or complete occlusion of the arterial lumen. "Because the relationship between GJA1 and the development of atherosclerosis has been previously reported, these findings suggested that GJA1 could be an important molecule mediating m6A regulation and the pathogenesis of MI." (PMID 38169719, 2024).
breast tumor (26 papers, 2005 to 2025). "To achieve this goal, we investigated Runx1 and Foxp3 participation in the regulation of expression of two tumor associated genes, Rspo3 and GJA1, which are known modulators of breast tumor cell growth (positively and negatively, respectively)." (PMID 26735887, 2016). "Consistent with the subtype-specific expression of Cx43, ERα- or PR-positive breast tumors had a significantly higher expression of GJA1 mRNA compared to ERα- or PR-negative tumors (Figure A1, Figure A2 and Figure A3)." (PMID 29495625, 2018). "We next compared transcript levels of GJA1 in breast tumor samples and in the non-cancerous adjacent tissues using microarray-based data of The Cancer Genome Atlas project (TCGA) breast invasive carcinoma cohort (BRCA) of clinical samples." (PMID 29495625, 2018). "Evidence suggests that Cx43 (GJA1) mRNA and protein expression is altered in breast tumors." (PMID 29312613, 2017).